SAMHD1 (SAM and HD domain containing deoxynucleoside triphosphate triphosphohydrolase 1)
Diseases named in the same sentence as SAMHD1 in open-access papers (continued):
Sharing a sentence is not in itself a finding about the gene and the disease.
infection (continued). "As a result of the absence of SAMHD1 the MDM of such patients support high levels of HIV-1 replication upon in vitro infection." (PMID 23497255, 2013). "This alteration generally disrupted the effect of Vpx on SAMHD1 and macrophage infection without reducing the steady state expression levels." (PMID 23497283, 2013). "Murine leukemia virus was restricted by SAMHD1 in macrophages yet removal of SAMHD1 did not alleviate the block to infection because of an additional block to viral nuclear import." (PMID 23497255, 2013). "The host protein SAMHD1 has been identified as the first mammalian deoxynucleoside triphosphate triphosphohydrolase (dNTPase), which blocks the infection of HIV-1 and other retroviruses in non-cycling immune cells." (PMID 24523981, 2013). "Immunoblotting of DC lysates from the same experiment indicated that de novo production of HIV-1 Gag p55 was significantly enhanced in SAMHD1 knockdown cells compared to negative controls, confirming productive infection." (PMID 23231760, 2012). "Prior to infection, cytokine and chemokine levels were low or undetectable in Donor 2, suggesting that the cells were not activated due to the absence of SAMHD1 (purple line)." (PMID 22174685, 2011). "At 4 and 6 dpi, we observed that the levels of BIK protein and mRNA in THP-1 Ctrl and SAMHD1 KI cells were higher than those in SAMHD1 KO and Lvx cells, regardless of HIV-1NL4-3 infection, suggesting that SAMHD1 increases BIK expression at both the protein and mRNA levels." (PMID 40434097, 2025). "Furthermore, SAMHD1 expression was reconstituted in SAMHD1 KO cells to confirm the role of SAMHD1 in mitochondrial depolarization with or without HIV-1-Luc/VSV-G infection." (PMID 40434097, 2025). "The expression of SAMHD1 protein was significantly downregulated with increasing infection dose, suggesting that H5N1 virus infection can downregulate SAMHD1 expression in A549 cells, and as the infection titer increases, the amount of SAMHD1 protein in the cells decreases." (PMID 38287375, 2024). "Therefore, the observed decrease in the ability of Vpx to rescue infection with time is likely independent of SAMHD1." (PMID 37127613, 2023). "This could explain why HIV-2 and some SIV retain Vpx or Vpr that can counteract SAMHD1, while HIV-1 does not and is susceptible to SAMHD1 activity, remaining a restriction factor for infection in certain cell types." (PMID 37766341, 2023). "Following infection with an HIV-1-GFP vector, HIV-1 restriction was measured using two-colour flow cytometry and an infectivity ratio was calculated by dividing the percentage of SAMHD1 positive cells infected with HIV-1 by the percentage of SAMHD1 negative cells infected with HIV-1." (PMID 37127613, 2023). "However, in differentiated cells, there is clearly increased reverse transcription in cells expressing the Tetunstable T592D mutant compared to the Tetstable T592C mutant or WT SAMHD1, again, regardless of the virus used in the infection." (PMID 37127613, 2023). "Importantly, we have shown that WT SAMHD1 is not just able to restrict infection of differentiated cells but can restrict HIV-1 in cycling cells when viral replication is sensitised to dNTP levels." (PMID 37127613, 2023). "In DC and macrophages cultured in vitro, the degradation of SAMHD1 by SIV-Vpx delivered in target cells by lentivectors prior to infection did not affect HTLV-1 infection, while it efficiently increased that of HIV, suggesting that SAMHD1 is not active against HTLV-1 in DC and macrophages." (PMID 35893677, 2022). "Overcoming the difference in infection levels in MDMs via dNTP addition and using a high ratio of Vpx−/Vpx+ viruses, we uncover an innate immune enhancement phenotype of Vpx that occurs even in the absence of SAMHD1." (PMID 33563288, 2021).
infection (continued). "SAMHD1 mRNA expression was analyzed in primary human foreskin fibroblasts (HFFs) and macrophage-derived THP-1 cells infected with laboratory or clinical HCMV strains and subjected to reverse transcription-quantitative PCR (RT-qPCR) analysis at day 1 and 2 post-infection (dpi)." (PMID 32986788, 2020). "At different time points post‐infection, we found that EV71 VP1 expression in HEK293T‐shSAMHD1 cells and supernatants was higher than those in HEK293T‐pLKO.1 control cells and supernatants at 48 h post‐infection, indicating that SAMHD1 inhibits EV71 replication." (PMID 31797533, 2020). "Importantly, complement-opsonized HIV-1 negatively regulates SAMHD1 in DCs by inducing its phosphorylation, which results in significantly higher DC infection with HIV-C compared to non-opsonized HIV-1, even though there is no Vpx." (PMID 33224139, 2020). "Having demonstrated that SAMHD1-mediated restriction is likely not the mechanism restricting productive infection in tonsillar CD127+ Tm cells, we tested the possibility that the block occurs later in the viral life cycle, after integration and provirus formation." (PMID 32353080, 2020). "In this regard, individuals infected by HTLV-1 with reduced SAMHD1 levels may have a greater proviral load, whereas increased enzyme expression may reduce viral replication and activate a potent type I IFN response, which would enable infection control." (PMID 32656092, 2020). "How pandemic HIV-1 strains achieve the efficient infection of terminally differentiated macrophages in vivo where SAMHD1 is active without a Vpx-like activity has remained a significant unresolved question that has limited our understanding of HIV tropism and pathogenesis." (PMID 32751972, 2020). "Moreover, we observed that in contrast to SAMHD1low cells, memory SAMHD1+ cells contain less Th17 in both infected and uninfected individuals (41% vs 15.4% and 55% vs 25%, respectively) and their depletion during infection was non-significant." (PMID 31220191, 2019). "Whether HIV-1 infection leads to DC maturation is unclear as it has been shown that interfering with SAMHD1 restriction increases infection of DCs but not DC maturation." (PMID 31354736, 2019). "In addition, although the phosphorylation status of SAMHD1 has been shown to affect its ability to restrict infection, our preliminary data do not show any change in phosphorylation status after infection by HIV-1 (data not shown)." (PMID 30656243, 2018). "Statistical comparison of Gag and SAMHD1 levels in SIV- and HIV-1-infected cells confirmed that not only do both HIV-1 and SIV infect macrophages at comparable levels (30% +/− 4.4% for HIV-1 and 48% +/− 6.1% for SIV), but only SIV infection of macrophages led to elimination of SAMHD1." (PMID 30656243, 2018). "Not surprisingly, SIVΔvpx did not affect SAMHD1 levels and was restricted from infection." (PMID 30656243, 2018). "SAMHD1 impedes infection of noncycling immune cells by HIV-1." (PMID 30044979, 2018). "To determine whether SAMHD1 activation results in a state of HIV-1 restriction that stems from limiting dNTP levels, we exposed cells to high concentrations of deoxynucleosides (dNs) in the culture medium prior to infection." (PMID 29764952, 2018). "We speculated that SAMHD1 upregulation is part of an early cellular response to infection that is independent of interferon." (PMID 27411355, 2016). "In contrast, viral RNA levels measured at 4 hr post-infection were not affected by SAMHD1." (PMID 27477283, 2016). "Interestingly, silencing of SAMHD1 significantly increased the level of released viral DNA compared to the control, suggesting that SAMHD1 mitigates the production or release of DNA-containing HBV particles in a bona fide infection model." (PMID 27229711, 2016).
infection (continued). "Even though HIV-1D185A/D186A/D443N infection of cells resulted in increased accumulation of viral RNA compared with that in cells infected with wild-type HIV-1, SAMHD1 still cleaved the viral RNA, indicating that SAMHD1 degrades HIV-1 RNA independently on HIV-1 RT." (PMID 26032178, 2015). "We next examined whether the RNase activity of SAMHD1 also controls infection by non-retro RNA genome viruses." (PMID 26032178, 2015). "Furthermore, RNAi-mediated SAMHD1 silencing fails to rescue myeloid cell infection in the presence of IFN." (PMID 24782834, 2014). "SAMHD1 has been described as suppressing the levels of dNTPs in several cell types and CRL degradation of SAMHD1 may elevate dNTP levels above the threshold required for retroviral reverse transcription and subsequent infection to proceed." (PMID 25314029, 2014). "Interestingly, our preliminary data futher suggest that APOBEC3A levels are upregulated when SAMHD1 is depleted, raising the possibility of a cooperation between the two restriction factors to counteract the infection (data not shown)." (PMID 23497353, 2013). "Similarly using differentiated THP-1 cells, the addition of Vpx or dNs, or SAMHD1 knock-down, also stimulated infection, but failing to match the levels observed without IFNα." (PMID 23442224, 2013). "In one case ineffective virion incorporation may have contributed to the lack of activity of the RH2-3 8A3 Vpx since changes of E15G and K68M restored its ability to degrade SAMHD1 but not to promote macrophage infection." (PMID 23497283, 2013). "To better understand the mechanism underlying SAMHD1-mediated HIV-1 restriction in DCs, we quantified the products of HIV-1 early and late reverse transcription over a time course ranging from 12 to 72 hr post-infection in the presence or absence of Vpx." (PMID 23231760, 2012). "Additionally, CD11c+ ASDCs expressed higher levels of the HIV restriction factor SAMHD1, which may further explain their lack of productive infection." (PMID 39861894, 2025). "Importantly, this cell-cell fusion process of MΦ infection is not restricted by the SAMHD1 restriction factor, suggesting that this mode of HIV-1 spreading in MΦ could be more efficient than cell-free infection." (PMID 35622876, 2022). "However, it remains unclear whether SAMHD1 phosphorylation plays a role in α-herpesviral infection at all, since Kim and colleagues found that the phosphorylation of SAMHD1 upon infection does not affect the SAMHD1-mediated restriction of HSV-1." (PMID 33801276, 2021). "Thus, HIV-1 may not have evolved an antagonist of SAMHD1 to avoid infection of myeloid cells and thus to escape from immune surveillance." (PMID 23497283, 2013). "Overall, the BIK mRNA levels were higher in THP-1 Ctrl cells compared to SAMHD1 KO cells, regardless of HIV-1NL4-3 infection or NVP treatment, suggesting that SAMHD1 increases BIK expression at the mRNA level." (PMID 40434097, 2025). "One possible explanation for the selective suppression of authentic SARS-CoV-2 infection but not ΔS-VRP(G) in SAMHD1 KO cells was due to abolished S-protein-mediated viral entry, which was not required for ΔS-VRP(G) infection." (PMID 41280104, 2025). "While SAMHD1 KO did not affect BLaER1 transdifferentiation, it strongly increased HIV-1-luc infection at 24 hpi, as compared to wild-type (WT) cells." (PMID 37800914, 2023). "Depletion of SAMHD1 D210A and D311A mutant protein by VLP-Vpx treatment did not further increase HIV-1-mCherry infection at MOI0.1." (PMID 37800914, 2023). "VLP-Vpx treatment led to efficient degradation of SAMHD1 (0.013 ± 0.007 relative SAMHD1 expression normalized to no VLP-Vpx, n = 3) and increased HIV-1-luc infection." (PMID 37800914, 2023). "They found that SAMHD1 was downregulated during efficient propagation of seasonal IAV, whereas this RF remained unaltered throughout non-permissive infections." (PMID 34490131, 2021).
infection (continued). "To overcome the difference in infection levels between viruses with or without Vpx, from here on we used undifferentiated THP-1 cells, where SAMHD1 is inactive due to the phosphorylation of a key residue." (PMID 33563288, 2021). "As a consequence of SAMHD1 restriction, the kinetics of HIV-1 RT reaction as well as the amount of HIV-1 RT products are limited in MDMs, when infections are initiated in the absence of SAMHD1 antagonism." (PMID 32630058, 2020). "While SAMHD1 did not inhibit Chikungunya and Zika viruses in human fibroblasts, it suppressed IRF7 phosphorylation and inhibited NF-kB activation after infection, thereby indirectly augmenting anti-viral defense." (PMID 31600877, 2019). "Collectively, these results indicate that HIV-1-infected macrophages remain restricted to infection by vpx-deleted SIV, and that HIV-1 infects macrophages without altering the SAMHD1 antiviral environment that otherwise completely restricts vpx-deleted SIV." (PMID 30656243, 2018). "However, Vpx, which should also promote HIV replication in resting T cells, did not appear to have a significant effect on viral levels in T cells, suggesting that SAMHD1 may not have been an important HIV restriction factor in tissue-resident T cells at least at an early time point after infection." (PMID 30532754, 2018). "Augmenting the viral inoculum to 500 ng p27 mL−1 did not improve the efficiency of infection, nor did pre-treatment of the cells with SIV-derived virus like particles carrying Vpx that completely down-regulated SAMHD1 (not shown)." (PMID 25582927, 2015). "Therefore, our data do not support the hypothesis that Vpx-mediated SAMHD1 degradation allows HIV-2 productive infection of MDDCs, and thus a potential difference in the ability of HIV-1 and HIV-2 to infect this cell type may not underlie differences in disease pathogenesis." (PMID 25582927, 2015). "We observed an increase in σ3 RNA levels at 24 h post-infection; however, the viral RNA kinetics in reovirus-infected THP-1 cells did not change after SAMHD1-depletion." (PMID 26032178, 2015). "Infection of SAMHD1Δ/Δ and control BMDCs with a third HIV reporter virus based on a different isolate (HXB2) showed moderate SAMHD1-mediated restriction in some experiments, but not in others (not shown)." (PMID 23972988, 2013). "To test whether Vpx VLP targeting of SAMHD1 could enhance HIV infection in microglia, we developed a novel model of infection." (PMID 41118075, 2025). "Therefore, to test this and rule out any late acting SAMHD1 nuclease activity, we used Nevirapine to block HIV-1 replication in U937 cells and monitored the recovery of infection following its removal at various times." (PMID 37127613, 2023). "However, this block to infection was abrogated by SIV VLP Q76A, even though SAMHD1 was not degraded." (PMID 29084722, 2018). "Thus, although single round infection of macrophages is improved by Vpx, carrying Vpx does not tend to rescue HIV-2 or SIVsm replication in DNA sensing competent cells such as macrophages, irrespective of its anti-SAMHD1 activity." (PMID 35073912, 2022). "Some data suggest that only the HD domain is required for inhibition of infection and that removing the C-terminal region does not affect restriction, while other studies suggest that the SAM domain may influence function and that the C-terminal region is required for SAMHD1 activity in cells." (PMID 26431200, 2015).
cancer (89 papers, 2013 to 2025). A tumor composed of atypical neoplastic, often pleomorphic cells that invade other tissues. "SAMHD1 expression is commonly elevated in various types of cancer, and its increased levels are associated with poor patient survival." (PMID 41392286, 2025). "The loss of the tumor suppressor SAMHD1 in cancers similarly results in R-loop accumulation and IFN production." (PMID 40629041, 2025). "Loss-of-function SAMHD1 mutations occur in several cancer types, including lymphocytic leukemia, lung, and colon cancer." (PMID 40519286, 2025). "Noteworthy, our data are in consonance with previously published data from The Cancer Genome Atlas database, where high SAMHD1 expression was associated with reduced OS in adult white cancer patients." (PMID 37667113, 2024). "Recently, the human sterile alpha motif and HD-domain-containing protein 1 (SAMHD1) has been linked to cancer onset and progression, as well as to chemosensitivity to distinct anticancer drugs, with numerous and controversial evidences." (PMID 37667113, 2024). "Among a wide range of investigated cancer cell lines in the Cancer Cell Line Encyclopedia, T-cell acute lymphoblastic leukemia cells show significantly lower expression of SAMHD1, which has been linked to AraG’s selectivity for activated T cells." (PMID 39089813, 2024). "Mutations in SAMHD1 in different cancer tissues have also been reported by the Catalogue of Somatic Mutations in Cancer (COSMIC)." (PMID 39206868, 2024). "Since the oncogenic effects of SAMHD1 mutations have already been reported in some cancer types, we investigated the occurrence of SAMHD1 mutations in RCC using the TCGA database." (PMID 37009792, 2023). "Although SAMHD1 mutations have been identified in various cancer types, their role in cancer is unclear." (PMID 37009792, 2023). "Additional noteworthy findings from our analyses of all multiple primary cancers combined include cancer susceptibility signals in SAMHD1 and SLC6A2, both having a significantly higher risk being diagnosed with multiple cancers compared to single cancers." (PMID 36199081, 2022). "Fourth, we found that rare variants in SAMHD1 not only affect mtDNA-CN levels but also confer risk to cancer." (PMID 35023831, 2022). "To investigate the mutation spectrum of SAMHD1 in cancer, we queried the International Cancer Genome Consortium (ICGC) database." (PMID 34480199, 2022). "(B) Manhattan plot showing phenome-wide significant associations between SAMHD1 carrier status and cancer-related phenotypes." (PMID 35023831, 2022). "The cytosolic DNA sensing STING pathway was required in the IFN-I response in SAMHD1-deficient mice and cancer cells." (PMID 36578072, 2022). "SAMHD1 promotes resistance to dNTP analog chemotherapy, and its mutations have been linked to human cancers, exhibiting its relevance beyond viral infection and importance to cancer." (PMID 36139652, 2022). "In the next chapter, we will discuss the impact of cancer-associated mutations on specific functions of SAMHD1." (PMID 34480199, 2022). "SAMHD1 downregulation has also been linked to protection of cancer development in patients casting doubt on the role of SAMHD1 as a tumor suppressor and highlighting the need of further evaluating its clinical significance in different tumor types." (PMID 35158911, 2022). "Recently, a structural and functional investigation of two cancer-associated SAMHD1 mutants showed that the R366C/H mutants possessed protein-stability profiles similar to the wild type, and their only functional deficit was a dNTPase deficiency." (PMID 35893688, 2022). "As outlined in this review, SAMHD1 has been reported to be mutated in a variety of cancer types and the expression of SAMHD1 is dysregulated in many cancers." (PMID 34480199, 2022). "In the publicly available database of the Cancer Genome Atlas (TCGA), 444 SAMHD1 somatic mutations were found in cancers varying from hematological malignancy to solid tumors." (PMID 34976810, 2021).